IDH1 (isocitrate dehydrogenase (NADP(+)) 1)
Diseases named in the same sentence as IDH1 in open-access papers (continued):
Sharing a sentence is not in itself a finding about the gene and the disease.
glioblastoma (continued). "Favorable prognostic value of IDH1 mutation was also recently demonstrated in pediatric glioblastomas." (PMID 26452024, 2016). "IDH1 mutation was found to have more dominant prognostic effect than histological grade in anaplastic astrocytomas and glioblastomas." (PMID 26369702, 2015). "Mutations in isocitrate dehydrogenase 1 and 2 (IDH1/2) are present in gliomas and in glioblastoma multiforme (GBM)." (PMID 26703582, 2015). "The frequency of IDH1 mutations in recurrent glioblastomas was nearly twice that in primary glioblastomas." (PMID 26427041, 2015). "Case 1 is histologically classified as astrocytoma with IDH1 mutation and intact 1p19q status, which progressed to anaplastic astrocytoma followed by glioblastoma." (PMID 26524630, 2015). "Some of these such as IDH1 mutations in glioblastoma are widely known; for others such as BRCA2 and NCOA3 mutations in ovarian cancer there is some evidence in the literature; while the remaining are genuinely novel." (PMID 25950620, 2015). "Nobusawa proposed that these primary glioblastomas with IDH1 mutation actually represent secondary glioblastomas with an unusually short clinical presentation." (PMID 27275230, 2015). "Examples include a glioblastoma (GBM)-selective module in which IDH1 mutation was directly linked to over 600 cis-located promoter methylations." (PMID 25953855, 2015). "Recent studies have pointed out the causal role of IDH1 mutations in Glioblastoma-CIMP and tight associations between IDH2 and TET2 mutations with other CIMPs (leukemia, enchondroma, and spindle cell hemangioma)." (PMID 26463173, 2015). "IDH1 hotspot mutations at R132 correlate with a glioblastoma hypermethylation phenotype and have been reported in melanoma." (PMID 26545983, 2015). "Multivariate analysis showed that KPS, adjuvant treatment and IDH1-R132H mutation were independently associated with OS in glioblastoma." (PMID 25880463, 2015). "Glioblastoma can occur either de novo or by the transformation of a low grade tumour; the majority of which harbor a mutation in isocitrate dehydrogenase (IDH1)." (PMID 25849605, 2015). "The expression levels of LOX, BMP1 and HIF1A were correlated and analyzed according to IDH1 mutation status and to the clinical end-point of overall survival of glioblastoma patients." (PMID 25790191, 2015). "There was only one pediatric primary glioblastoma and a recurrent case of pilocytic astrocytoma which expressed the IDH1 mutation." (PMID 27275230, 2015). "Wild-type IDH1/2 and mutated TERTp were identified in up to 80% of glioblastomas and was associated with poor prognosis in patients with the grade IV tumors." (PMID 26369702, 2015). "The new era of cancer genomics, due to the revolution of next generation sequencing, was heralded in 2008 by the discovery of mutations in the IDH1 gene in glioblastomas (GBM)." (PMID 25849072, 2015). "Recently, missense mutations in IDH1 were identified in a significant number of glioblastomas that tended to occur mostly in younger patients with more protracted clinical courses." (PMID 25908947, 2015). "Glioblastoma with a mutation in IDH1 expressed lower levels of LOX in the nucleus, and IDH1-mutated cases showed lower LOX expression levels when compared to wild-type IDH1 cases." (PMID 25790191, 2015). "Metabolomic profiling of U87MG glioblastoma cells expressing these mutations in IDH1 determined the structural change of the mutated protein results in acquisition of the ability to convert α–ketoglutarate to R(-)-2-hydroxyglutarate (2HG)." (PMID 25923219, 2015). "To illustrate how a module can be analyzed in greater detail, we next focus on the the glioblastoma-specific module defined by IDH1 mutation (module vii)." (PMID 25953855, 2015).
glioblastoma (continued). "In the primary brain tumors group, IDH1 mutations are presented mostly in diffuse astrocytomas (64%), anaplastic astrocytomas (49%), glioblastomas (9%), or oligodendrogliomas (2%)." (PMID 24511544, 2014). "This recently described mutation in isocitrate desidrogenase enzyme type 1 (IDH1) seems to be frequent in diffuse gliomas of astrocytic and oligodendroglial lineage, as well in those secondary glioblastomas that derive from such tumors." (PMID 25482099, 2014). "For instance, these genetic events are predominant in thyroid cancer carrying the mutation in the genes of the RAS-BRAF signalling pathway, and in glioblastoma with the mutation in the IDH1 gene." (PMID 24742867, 2014). "Our results are in accordance with those already described, since this was a case of primary glioblastoma, and also show that xenografts are able to keep the IDH1 mutation status of highly aggressive tumors." (PMID 25482099, 2014). "The IDH1 R132H mutation occurred in 4 of 26 primary GBMs (15.3%), whereas the majority, 16 of 18 (89.9%) were of secondary glioblastomas mutated." (PMID 24511544, 2014). "The discovery of IDH1 mutations has allowed the categorization of biological subgroups of glioblastoma based on different cellular origins." (PMID 25411563, 2014). "In cases of acute myeloid leukemia and glioblastoma, the IDH1/2 mutation results in the formation of 2-OH-glutarate, which is a competitive inhibitor of α-KG–dependent processes, especially demethylation of histones." (PMID 25127496, 2014). "Several previous studies have demonstrated the important role of IDH1/IDH2 mutations for determining the prognosis of glioblastoma patients." (PMID 24868540, 2014). "In the present study, the frequency of IDH1/2 gene mutations in astrocytoma, anaplastic astrocytoma, primary glioblastoma and secondary glioblastoma was 82.5% (33/40), 27.3% (6/22), 17.3% (14/81) and 68.4% (13/19), respectively." (PMID 24810474, 2014). "The somatic mutation affecting amino acid 132 in the isocitrate dehydrogenases 1 gene (IDH1) is also associated with a better clinical outcome in gliomas, including glioblastoma." (PMID 25233099, 2014). "Isocitrate dehydrogenase 1 (IDH1) gene mutations are found in 60 – 90% of diffuse and anaplastic gliomas and secondary glioblastomas." (PMID 23442355, 2013). "As another example, isocitrate dehydrogenase 1 (IDH1) is a metabolic enzyme with frequent R132H mutations in leukemia and glioblastoma that associate to altered DNA methylation." (PMID 24089029, 2013). "Glioblastoma samples with confirmed mutations of the IDH1 or IDH2 gene was used as positive controls." (PMID 24386123, 2013). "As IDH1/2 mutations are frequent (>80%) in secondary glioblastomas that have progressed from low-grade or anaplastic astrocytomas, it suggests that these tumors share a common progenitor cell population." (PMID 24202337, 2013). "Isocitrate dehydrogenase 1 (IDH1) gene mutations occur in ~ 60 – 90% of diffuse and anaplastic gliomas and secondary glioblastomas." (PMID 23442355, 2013). "IDH mutations in AML correlate with a similar hypermethylator phenotype to TET2 mutations and CIMP in glioblastoma is also associated with IDH1 mutations." (PMID 23341493, 2013). "Our observations link young adults with IDH1 mutation with specific morphological features of glioblastoma to these hypoxic, glomeruloid patterns of vascular proliferation." (PMID 23451042, 2013). "In the present study, we noted strong associations of glioblastoma in young adults to harbour IDH1 mutation, prominent oligodendroglial and small cell tumour cell morphology, and glomeruloid vascular proliferation." (PMID 23451042, 2013). "Recent reports showed IDH1 mutations in astrocytic and oligodendroglial tumors (WHO grade II and III) and in secondary glioblastomas with a frequency of up to 90%, whereas IDH1 mutations occurred in only 5% of primary glioblastomas." (PMID 22427879, 2012).
glioblastoma (continued). "IDH1 codon 132 mutations were found to be associated with reduced NADP-dependent IDH activity in glioblastoma." (PMID 22427879, 2012). "The highest methylation level detected (5.3%) was in a secondary glioblastoma that harbored an IDH1 R132H mutation." (PMID 23267435, 2012). "In our cohort only one glioblastoma in the highest quartile of staining was positive for the IDH1 R132H mutation." (PMID 22829908, 2012). "In glioblastoma, low 5hmC is associated with reduced survival even after controlling for IDH1 mutation status, age at diagnosis, and gender." (PMID 22829908, 2012). "We also observed a strong haplotype association for IDH1; a somatic mutation in IDH1 has been linked to survival in adult glioblastoma and AML." (PMID 22674224, 2012). "Most grade III astrocytomas and a minority of glioblastomas carry a mutation affecting codon 132 of the IDH1 gene resulting in an amino acid change (R132H, R132S, R132C, R132G, or R132L)." (PMID 23046790, 2012). "In fact, in oligodendrogliomas and secondary glioblastomas, mutations in the IDH1 gene that inactivate the IDH1 catalytic activity have been reported." (PMID 21655185, 2011). "The latest WHO classification adopts a multi-layer integrated approach to defining glioblastoma, integrating histological features with molecular signatures: IDH-1 mutation, EGFR amplification, TERT promoter mutations, and the combined gain of chromosome 7 and loss of chromosome 10." (PMID 41008823, 2025). "Although PD-L1 expression in glioblastoma has been recognized as a possible therapeutic target, more research is needed to fully understand its relationship to tumor grade and molecular features like isocitrate dehydrogenase (IDH1 R132H) mutations." (PMID 39906459, 2025). "The same study also focused on glioblastomas categorized by age and IDH1 mutation status." (PMID 39165459, 2024). "Additionally, patients with glioblastomas showing low MMP-9 expression were generally younger and had higher rates of MGMT promoter methylation and IDH1 mutations compared to patients with glioblastomas with high MMP-9 expression." (PMID 39684754, 2024). "Therefore, in this cohort, we cannot distinguish between the impact of IDH-1 mutation or wild type on different glioblastoma age groups." (PMID 38539563, 2024). "Further analysis also revealed that the effects of anti-VEGF therapy may be dependent on the glioblastoma genetic subtypes, e.g., IDH1 mutation status, suggesting the necessity of patient subtype stratification before clinical trials." (PMID 39061427, 2024). "The validity of the conclusion for primary glioblastoma, however, is questioned by the use of the IDH1 mutation as a marker for tumour cells since IDH1 mutations in glioblastoma confer to a genetically distinct and infrequent subset of glioblastoma, with better survival outcomes being predicted." (PMID 38275817, 2024). "This suggests a significantly lower risk ratio (p < 0.05), indicating that glioblastoma patients with the IDH1 mutation may have a higher survival rate." (PMID 38418842, 2024). "In primary glioblastoma, less than 10% of tumors have a mutation in IDH1." (PMID 37046844, 2023). "Also, glioblastoma patients diagnosed with IDH1/2 mutations usually have a better prognosis and longer mean survival times than patients in IDH1/2 wildtype cases in the same clinical grades." (PMID 37546420, 2023). "This attribute gains importance given that, amongst WHO Grade 2/3 astrocytomas, oligodendrogliomas, and glioblastomas developing from these lower grade entities, IDH1 mutation occurs at codon number 132 in over two-thirds of these, with IDH2 mutations occurring in 6% of them." (PMID 36831683, 2023).
glioblastoma (continued). "Moreover, as a key oncogenic miRNA in glioblastoma pathogenesis, miR-21 was significantly up-regulated by IDH1 mutations (log-fold change 0.86, adjusted P = 4.5 × 10−77)." (PMID 37624931, 2023). "In contrast, in primary glioblastoma, less than 10% of tumors have IDH1 mutation." (PMID 37046844, 2023). "Genetic abnormalities of the IDH1 coding gene are also frequent in glioblastoma; these mutations reduce the affinity of the active site of IDH1 for isocitrate while conversely increasing the affinity for nicotinamide adenine dinucleotide phosphate (NADPH) and α-ketlutogarate (α-KG)." (PMID 37759505, 2023). "Tumor PGBM underwent extensive histopathological and genomic analysis for clinical purposes and demonstrated diffuse and high-grade glioblastoma histology, IDH1 mutation (IDH1 c.395G>A [p.Arg132His]), MGMT promoter methylation profile, TERT promoter wild-type, and absence of 1p/19q codeletion." (PMID 37192626, 2023). "Therefore, we excluded glioblastomas with prior IDH1 mutations from the TCGA and CGGA glioblastoma datasets." (PMID 37626511, 2023). "Finally, mutations in the IDH1/2 genes are frequently found in a distinct subtype of glioblastomas, characterized by the younger age of onset and longer survival." (PMID 35806153, 2022). "In the TCGA annotation, the IDH1/2 mutation status was unknown for 119 glioblastomas, one oligodendroglioma, and one astrocytoma case." (PMID 36613601, 2022). "Recently published work from our laboratory showed that PARP and ATR inhibitors synergize in the common glioblastoma mutation in isocitrate dehydrogenase 1/2 (IDH1/2), so perhaps MMR-deficiencies may also benefit from this combination." (PMID 35388070, 2022). "Mutations in IDH1 were first reported in a genome‐wide analysis of patients with glioblastomas." (PMID 35526267, 2022). "However, it must be stressed that the presence of IDH1 mutation now precludes the formal pathological diagnosis of glioblastoma, as it is now genetically defined as “IDH-wildtype” in the most recent edition of the WHO Classification of CNS Tumors." (PMID 36591531, 2022). "As our glioblastoma cohort contained only 3 IDH1 mutant tumours, the impact of the IDH1R132H mutation on HIF-hydroxylase activity, or on the association between ascorbate and the HIF-pathway, is intriguing but could not be assessed." (PMID 35419292, 2022). "Moreover, in the frontal lobe, localized in the left hemisphere, MGMT-methylated, IDH1-mutated glioblastomas appeared." (PMID 35330402, 2022). "IDH1 mutation molecular subtypes and Proneural histological types were significantly associated with better survival in glioblastoma, whereas IDH1 wild molecular subtypes and Mesenchymal histological types were significantly associated with worse clinical outcome." (PMID 35359993, 2022). "However, although IDH1/2 mutations are associated with better prognosis of glioblastoma patients, their impact on prognosis and response of AML to treatment is still unclear." (PMID 35740380, 2022). "More than 70% of the WHO grade II and III astrocytomas, oligodendrogliomas, and glioblastomas originating from these low-grade lesions have mutations affecting amino acid 132 of IDH1, and alterations affecting IDH2-like amino acids R172 are common in tumors without IDH1 mutations." (PMID 35769466, 2022). "Moreover, inhibiting glutaminase by siRNA or BPTES markedly slowed the growth of IDH1-mutated glioblastoma cells when compared to those expressing wild-type IDH1." (PMID 34425876, 2021). "IDH1 mutations were first discovered in glioblastoma genome-wide analysis." (PMID 33981605, 2021). "We identify H3.3G34R and IDH1/2 mutations as two such factors in ATRX-mutated glioblastomas." (PMID 33972520, 2021).
glioblastoma (continued). "Therefore, out of the 104 glioblastoma cases, 62 (59.0%) were wild-type for IDH1 and 42 (40.2%) carried an IDH1 mutation." (PMID 34030435, 2021). "Indeed, there is a phase 1–2 trials to test metformin in glioblastoma-solid tumor patients with IDH1 or IDH2 mutated." (PMID 35008275, 2021). "However, an untargeted metabolomic study using LC–MS was conducted that compared glioblastoma cells that were either WT for IDH1 or with the R132H, R132C, R132L or R132S mutations." (PMID 34200553, 2021). "Additionally, IDH1 mutations have been identified in glioblastomas developed from WHO grade II/III astrocytomas or oligodendrogliomas." (PMID 32102285, 2020). "Especially among glioblastomas, GSCs with an IDH1 mutation were less dependent on E&F than those with wildtype IDH1, indicating that GSCs could show distinct gene expression patterns and dependency on E&F according to their IDH1 mutation status." (PMID 32120790, 2020). "Furthermore, the monocarboxylate transporters 1 and 4 (MCT1 and MCT4, encoded by SLC16A1 and SLC16A3, respectively) that are typically overexpressed in glioblastomas, are underexpressed or silenced in glioblastomas that possess IDH1 mutations." (PMID 33019704, 2020). "IDH1 mutations were found in 12% of glioblastoma patients by second-generation sequencing." (PMID 33718116, 2020). "In a previous study, we demonstrated that a high mHsp70 expression was also found on primary glioblastoma cells without isocitrate-dehydrogenase 1 (IDH-1) mutation, whereas secondary glioblastoma with IDH-1 mutation and low-grade anaplastic gliomas exhibited a lower mHsp70 density." (PMID 32276468, 2020). "Similarly to what we observed in vitro, the PDX with the IDH1R132H mutation had lower protein levels of NAMPT compared to the IDH1-wildtype glioblastoma." (PMID 31888244, 2019). "Moreover, the patients of glioblastoma with IDH1 mutation and ALT activation, which is associated with longer telomeres, showed better clinical outcome than those with ALT-negative tumor." (PMID 30709063, 2019). "Our results support high ALDOC expression in glioblastomas that might imply the mutated status of IDH1, less possibility of mesenchymal subtype, and predict a favorable prognosis." (PMID 31450822, 2019). "Besides, ALDOC showed an inversed trend of mutation status of IDH1 in glioblastomas (Spearmen rho = ~0.169, p = 0.001)." (PMID 31450822, 2019). "In addition, our results also show that the expression of ALDOC was associated with IDH1 genomic alteration event in glioblastomas." (PMID 31450822, 2019). "In this sense, a technique comparison study comprising 62 glioblastoma samples to detect IDH1 mutations by Sanger direct sequencing, ddPCR or quantitative real-time PCR (qRT-PCR) showed that ddPCR was more sensitive method to screen for IDH1 mutations." (PMID 31284524, 2019). "In 2008, next-generation sequencing identified recurrent mutations in isocitrate dehydrogenase 1 (encoded by IDH1) in a subset of glioblastoma cases, mostly from younger patients with a history of prior lower-grade astrocytoma (clinically referred to as secondary glioblastoma)." (PMID 30967140, 2019). "However, we exclusively included grade IV glioblastomas and just one patient carried an IDH1-mutation in this study." (PMID 29983895, 2018). "From a precision diagnostics perspective, our results indicate that sub-categorization of glioblastoma by taking both IDH1 mutation status and imaging subtype might provide a more precise diagnosis, as well as more accurate prognostication." (PMID 29572492, 2018). "Low efficacy of penfluridol against pediatric tumor may in part be attributed to the fact that one third of pediatric glioblastoma is characterized by H3F3A mutations, whereas IDH1-mutated glioblastoma is common in adult patients." (PMID 28380428, 2017). "This could be attributed to the fact that H3F3A mutations are common in pediatric glioblastoma, whereas IDH1 mutations are common in adult glioblastoma tumors." (PMID 28380428, 2017).